ADAM19 (ADAM metallopeptidase domain 19)
Description:
Participates in the proteolytic processing of beta-type neuregulin isoforms which are involved in neurogenesis and synaptogenesis, suggesting a regulatory role in glial cell. Also cleaves alpha-2 macroglobulin. May be involved in osteoblast differentiation and/or osteoblast activity in bone (By similarity).
Synonyms: MADDAM; MLTNB; FKSG34
Tractability: Antibody: its Gene Ontology location is reachable by antibodies, with high confidence; UniProt predicts a signal peptide or a membrane-spanning region. PROTAC: ubiquitination databases record sites on it.
Gene: Protein-coding gene on chromosome 5 (157,395,534 to 157,575,858, reverse strand). Ensembl gene ENSG00000135074.
Subcellular location: Membrane
Subcellular location (Human Protein Atlas): Vesicles
Pathways (Reactome):
Cell-Cell communication: Regulation of CDH11 function
Extracellular matrix organization: Invadopodia formation
Gene Ontology:
Molecular function: metalloendopeptidase activity; protein binding; metallopeptidase activity
Biological process: amyloid precursor protein catabolic process; placenta development; positive regulation of cell-cell adhesion mediated by cadherin; positive regulation of gene expression; protein processing; membrane protein ectodomain proteolysis; proteolysis
Cellular component: extracellular matrix; nucleus; plasma membrane; membrane
Genetic constraint (gnomAD): Loss-of-function variants: 70 observed, 115.54 expected, observed/expected ratio (o/e) 0.61, 90% interval 0.5 to 0.74. The upper end of that interval is the gene's LOEUF score, 0.74, which puts it in group 3 of 6, group 1 being the genes least tolerant of losing a copy. Missense variants: 1,063 observed, 1,207.4 expected, observed/expected ratio (o/e) 0.88, 90% interval 0.84 to 0.93. Synonymous variants: 466 observed, 455.06 expected, observed/expected ratio (o/e) 1.02, 90% interval 0.95 to 1.11.
Homologues: Orthologues: chimpanzee ADAM19 (99% identical), macaque ADAM19 (98% identical), pig ADAM19 (89% identical), rabbit ADAM19 (86% identical), dog ADAM19 (86% identical), rat Adam19 (84% identical), guinea pig ADAM19 (80% identical), tropical clawed frog adam19 (50% identical), zebrafish adam19b (48% identical). Paralogues in human: ADAM12 (42% identical), ADAM33 (37% identical), ADAM15 (33% identical), ADAM9 (31% identical), ADAM8 (31% identical), ADAM22 (27% identical), ADAM28 (27% identical), ADAM11 (26% identical), ADAM23 (25% identical), ADAM20 (24% identical), ADAM29 (24% identical), ADAM30 (23% identical), and 8 more.
Diseases named in the same sentence as ADAM19 in open-access papers:
ADAM19 is named in the same sentence as 81 diseases in open-access papers, as found by Europe PMC text mining. Sharing a sentence is not in itself a finding about the gene and the disease. The quoted sentences say what the papers report.
glioblastoma (23 papers, 2017 to 2025). The most malignant astrocytic tumor (WHO grade IV). "Low levels of METTL3 or METTL14, key components of the RNA methyltransferase complex, have been shown to reduce the expression of m6A-modified ADAM19 RNA, whereas high ADAM19 RNA expression in glioblastoma stem cells causes glioblastoma." (PMID 34136491, 2021). "A study showed that low levels of METTL3 or METTL14, key components of the RNA methyltransferase complex, lead to decreased m6A modification levels on ADAM19 and the enhanced expression of ADAM19 in GSCs, ultimately causing glioblastoma." (PMID 30031372, 2018). "Likewise, the inhibition of FTO has been shown to prevent GSC growth, self-renewal, and tumorigenesis; FTO is associated with poor survival due to its regulation of ADAM19, a gene with key biological functions in glioblastoma stem cells." (PMID 36360287, 2022). "Preliminary studies have shown that m6A methylation inhibits the self-renewal, progression, and tumorigenesis of glioblastoma stem cells by reducing the stability and expression of major ADAM19 oncogenic transcripts." (PMID 36360287, 2022). "Another salient example lies in glioblastoma; METTL3/14 knockdown can promote tumorigenesis for glioblastoma stem cell (GSC) by decreasing m6A modification in the mRNA of the targeted oncogene ADAM metallopeptidase domain 19 (ADAM19)." (PMID 34895230, 2021). "METTL14 knockdown had a positive impact on glioblastoma stem cell growth by decreasing the expression of ADAM19 in an m6A-dependent manner." (PMID 34699322, 2021). "Downregulation of METTL3 or METTL14 can promote proliferation and self-renewal of glioblastoma stem cells by reducing the m6A level on ADAM19 mRNA, which enhances its stability and finally promotes the occurrence of glioblastoma." (PMID 34900689, 2021). "ADAM19 is a metalloproteinase disintegrin gene that exhibits elevated expression in glioblastoma cells and promotes glioblastoma cell growth and invasiveness." (PMID 29587823, 2018). "In the present study, we evaluated the expression of miR-145 and A Disintegrin and Metalloproteinase 19 (ADAM19) in glioblastoma multiforme (GBM) tissues and cells." (PMID 29190936, 2017). "For example, the mRNA of ADAM19, a metalloproteinase disintegrin gene that exhibits elevated expression in glioblastoma cells and promotes glioblastoma cell growth and invasiveness, is m6A methylated." (PMID 28297667, 2017). "MiR-145 could inhibit cell invasion and migration by targeting TWIST in Colorectal Cancer, TGFBR2/Smad3 axis in bladder cancer, phospholipase C epsilon 1 in esophageal squamous cell carcinoma, ADAM19 in glioblastoma, and TGF-β1 in breast cancer." (PMID 32083506, 2020). "For example, in glioblastoma cells, ADAM19 is an oncogene that promotes tumor progression." (PMID 31798620, 2019). "Low m6A modification levels on ADAM19 and high mRNA expression levels of ADAM19 may represent a promising target for anti-glioblastoma therapy." (PMID 30031372, 2018). "Thus, m6A-modified ADAM19 could represent a potential drug target for treating glioblastoma ass its downregulation could prevent tumor development." (PMID 34136491, 2021). "A similar finding is indicated for glioblastoma stem cells, METTL14 knockdown could enhance glioblastoma stem cell growth, self-renewal and tumorigenesis by enhancing m6A modification of ADAM19 and decreasing its expression, suggesting a tumor suppressor role of METTL14." (PMID 33430867, 2021). "For example, in glioblastoma multiforme (GBM), METTL3 suppresses the proliferation and self-renewal of glioblastoma stem cells by enhancing m6A modification of ADAM19 and decreasing its expression, which suppressed the progression of GMB." (PMID 35281815, 2022). "For example, in glioblastoma multiforme (GBM), the downregulation of m6A leads to decreased levels of the ADAM19 gene, enhancing its expression." (PMID 35563821, 2022).
glioblastoma (continued). "As is the case of METTL3 in glioblastoma, METTL14 depletion facilitates the malignant phenotype, characterized by upregulated oncogenes such as ADAM19 and reduced expression of tumor suppressors such as CDKN2A." (PMID 31921664, 2019). "By decreasing m6A levels of ADAM19 and increasing its expression in glioblastoma stem cells (GSCs), downregulation of METTL3/14 stimulates the proliferation and self-renewal of GSCs, ultimately resulting in GBM." (PMID 35159736, 2022).
glioma (8 papers, 2019 to 2025). A benign or malignant brain and spinal cord tumor that arises from glial cells (astrocytes, oligodendrocytes, ependymal cells). "In addition, low levels of METTL3 or METTL14 lead to decreased m6A modifications on ADAM19 and increased level of ADAM19 in GSCs, ultimately causing glioma." (PMID 33718165, 2021). "After METTL3 knockdown, ADAM19 expression increases, which promotes the occurrence of glioma." (PMID 40469294, 2025). "In addition, ADAM8 and ADAM19 are correlated with the invasive activity of glioma cells and unfavorable survival, while ADAM9, -10 and -17 are associated with tumor grade and histological type of gliomas and can be used as prognostic factors." (PMID 34638718, 2021). "Reduced m6 A levels in ADAM19 mRNA and in FOXM1 promote glioma stem cell proliferation and self‐renewal and ultimately lead to tumorigenesis." (PMID 40382536, 2025). "Additionally, the protease activities and expression levels of ADAM8 and ADAM19 correlated with invasive activity of glioma cells, which suggests that these proteins might play a significant role in tumor invasion and may be associated with unfavorable survival." (PMID 34638718, 2021). "ADAM8 and ADAM19 are correlated with the invasive activity of glioma cells and may be associated with unfavorable survival, while ADAM9 is associated with tumor grade and histological type in gliomas and might be an independent prognostic factor, especially in LGG patients." (PMID 34638718, 2021). "Additionally, the expression of ADAM19 is increased after METTL14 knockdown, which promotes the occurrence of glioma." (PMID 40469294, 2025).
brain tumors (7 papers, 2014 to 2023). "This pertains also to ADAM19, which has previously been shown to be overexpressed in brain tumors and implicated as a promoter of invasion." (PMID 36890812, 2023). "ADAM19 is highly expressed in human primary brain tumours, and expression and activity are associated with invasiveness." (PMID 25375322, 2014). "Another study reported the significance of ADAM19 and its proteolytic activity in brain tumors." (PMID 37835389, 2023). "In addition, ADAM19 was found to be up-regulated in renal cell carcinoma and primary brain tumors and promoted the invasiveness of the tumors." (PMID 25799050, 2015). "ADAM19 was described as up-regulated in human brain tumours and correlating with its invasiveness." (PMID 26482227, 2015).
breast cancer (7 papers, 2017 to 2024). A primary or metastatic malignant neoplasm involving the breast. "Indeed, high ADAM19 expression was shown to be associated with brain metastasis in breast cancer, suggesting that the increased ADAM19 expression promotes metastatic potential of the H2BE76K mutant cells." (PMID 33548228, 2021). "In the breast cancer cell line, the transcription of ADAM19 (a disintegrin and metalloproteinase-domain-containing protein 19), a cancer-associated gene, increases by H2BE76K mutation through facilitation of transcription elongation processes." (PMID 39439908, 2024). "Independent of PTHrP, ADAM19 is also implicated in the oncogenic properties of breast cancer." (PMID 38331475, 2024). "Previous mechanistic research has shown that miR-145 could regulate cell proliferation by targeting TGF-β1 in breast cancer, by targeting NRAS in condyloma acuminatum, and by regulating ADAM19 in retinoblastoma." (PMID 32614357, 2020).
colorectal cancer (7 papers, 2015 to 2023). A primary or metastatic malignant neoplasm that affects the colon or rectum. "High expression of miR-148a is found to be associated with progression in colorectal cancer and miR-30c is involved with ADAM19 in colon cancer cell lines." (PMID 29152124, 2017). "Our data show that ADAM19 downregulation decreased HCT116 cell growth and clonogenic activity, which hints at a pro-tumorigenic function of ADAM19 in colorectal cancer." (PMID 36890812, 2023). "ADAM19 was also reported as a miRNA target in the treatment of several cancers such as colorectal cancer, non-small cell lung cancer, and retinoblastoma, with the goal to inhibit proliferation, migration and invasion." (PMID 32727620, 2020). "Likewise, a previous study and our data strongly suggest that ADAM19 is overexpressed in colorectal cancer and may be a predictor of survival." (PMID 36890812, 2023). "In addition, expression levels of ADAM10, ADAM17, and ADAM19 were elevated in human colorectal carcinoma biopsy specimens compared to adjacent non-tumorous tissues." (PMID 33043016, 2020).
asthma (4 papers, 2013 to 2025). "ADAM19 and IL-7R were also associated with asthma outcomes in the FinnGen database when the same variants identified in the primary analysis were used as exposure factors." (PMID 39806440, 2025). "Conversely, an increase in ADAM19 (OR = 0.87; 95% CI 0.82–0.92; P = 6.17 × 10−7) and Layilin (OR = 0.61; 95% CI 0.51–0.73; P = 1.14 × 10−7) decreased the risk of asthma." (PMID 39806440, 2025). "Specifically, in plasma, we found that an increase of one standard deviation in IL1R1 and ECM1 was associated with an increased risk of asthma, while an increase in ADAM19 was found to be protective." (PMID 37809092, 2023). "Many of the methylation sites we identified have been associated with asthma including ADAM19, EPX, IL4, IL5RA, and PRG2." (PMID 29692868, 2018). "Several of these methylation loci were previously associated with asthma (ADAM19, EPX, IL4, IL5RA, and PRG2)." (PMID 29692868, 2018). "Specifically, we identified multiple methylation loci in genes previously associated with asthma (ADAM19, EPX, IL4, IL5RA, and PRG2) from genome-wide and epigenome-wide association studies." (PMID 29692868, 2018). "Additionally, using the same analysis method in the FinnGen database, we found that IL1-R1, ADAM19, and IL7R were associated with asthma risk, further demonstrating the stability of the results obtained in this study." (PMID 39806440, 2025). "Interestingly MMP10 and ADAM19 gene expression has also been shown to be upregulated in pBECs from subjects with asthma." (PMID 23384071, 2013). "A causal relationship exists between genetically determined protein levels of IL1R1, IL7R, ECM1, CD200R1, ADAM19, IL-6 sRa, and Layilin (LAYN) and asthma." (PMID 39806440, 2025). "Our study demonstrated a causal relationship between genetic determinants, including IL1R1, IL7R, ECM1, CD200R1, ADAM19, IL-6 sRa, and Layilin (LAYN) protein levels, and asthma." (PMID 39806440, 2025).
colon cancer (4 papers, 2015 to 2023). "Overall, our study provides the new insight that miR-30c inhibited colon cancer cells via targeting ADAM19." (PMID 25799050, 2015). "The results showed that miR-30c plays a crucial role in a plethora of biological processes via regulation ADAM19 in human colon cancer." (PMID 25799050, 2015). "Further experiments demonstrated that the expression levels of miR-30c and ADAM19 were inversely correlated in several colon cancer cell lines and clinical tumor samples determined by qRT-PCR." (PMID 25799050, 2015). "And high ADAM19 expression appears to also be predictive of worse disease-free survival, although this does not reach statistical significance, suggesting that ADAM19 exerts pro-tumorigenic functions in colon cancer." (PMID 36890812, 2023). "Taken together, the present study shows for the first time that miR-30c suppresses cancer cell growth, migration and invasion by directly targeting ADAM19 which could promote the malignance of colon cancer cells." (PMID 25799050, 2015). "In our study, we found that ADAM19 could promote the invasiveness of colon cancer cells for the first time." (PMID 25799050, 2015). "Therefore, re-expressing miR-30c and/or interfering with ADAM19 function might be a promising colon cancer therapeutic strategy." (PMID 25799050, 2015).
lung carcinoma (4 papers, 2011 to 2020). "The lncRNA NORAD regulates lung cancer cell proliferation, apoptosis, migration and invasion via the miR‐30a‐5p/ADAM19 axis." (PMID 32569434, 2020). "Finally, survival analysis of lung cancer patients using the kmplot.com software showed that a high expression of genes involved in ECM degradation, such as ADAM19 (p = 3.3E−5), ADAMTS6 (p = 0.00032), or MMP9 (p = 0.04), was associated with a poor prognosis." (PMID 30814494, 2019). "This might explain why the lung cancer GWA studies to date failed to consistently identify the Chr4q31 (HHIP/GYPA) and Chr4q22 (FAM13A) loci as a protective loci, and the Chr 5q33 (ADAM19) locus as a possible susceptibility locus." (PMID 21304900, 2011).
renal fibrosis (4 papers, 2016 to 2025). A final common manifestation of a wide variety of chronic kidney diseases characterized by glomerulosclerosis and tubulointerstitial fibrosis. "The expression and effect of miR-335-5p and ADAM19 during renal fibrosis in vivo require further study." (PMID 35902972, 2022). "ADAM19 expression is induced by TGF-β1 and other fibrotic stimuli in alveolar epithelial cells and renal cells, and abolishment of ADAM19 expression counteracts renal fibrosis." (PMID 33552116, 2020). "No scholars have reported the association between ADAM19 and cardiac fibrosis, but some studies have revealed the potential role of ADAM19 in renal fibrosis and pulmonary fibrosis." (PMID 33552116, 2020). "ADAM19 is overexpressed in renal fibrosis where it is regulated by canonical TGF-β1 signaling." (PMID 27574697, 2016).
retinoblastoma (4 papers, 2020 to 2025). A malignant tumor that originates in the nuclear layer of the retina. "Noteworthy examples include circ_0000034, which accelerates RB development by upregulating ADAM19 expression, and circDHDDS, significantly up-regulated in RBs, promoting retinoblastoma proliferation." (PMID 40535798, 2025). "Furthermore, circular RNAs (circRNAs) can also serve as ceRNAs to regulate the proliferation and migration of retinoblastoma cells, such as the circDHDDS/miR-361-3p/WNT3A axis and Circ_0000034/miR-361-3p/ADAM19 axis." (PMID 34095180, 2021).
idiopathic pulmonary fibrosis (3 papers, 2020 to 2025). Idiopathic pulmonary fibrosis (IPF) is a nonneoplastic pulmonary disease that is characterized by the formation of scar tissue within the lungs in the absence of any known cause. "Furthermore, SSc patients’ skin ADAM19 expression was negatively correlated with FVC and DLco, indicating that ADAM19 positively correlated with lung fibrosis severity." (PMID 39716051, 2024). "Studies showed that ADAM19 expression was upregulated in alveolar epithelial cells by TGF-β and played a role in the deposition of collagen and ECM in idiopathic pulmonary fibrosis, the most common type of ILD." (PMID 39716051, 2024).